CALML5 (calmodulin like 5)
Description:
Binds calcium. May be involved in terminal differentiation of keratinocytes.
Synonyms: CLSP
Tractability: Antibody: its Gene Ontology location is reachable by antibodies, with high confidence; the Human Protein Atlas places it where antibodies can reach.
Gene: Protein-coding gene on chromosome 10 (5,498,697 to 5,499,570, reverse strand). Ensembl gene ENSG00000178372.
Subcellular location (Human Protein Atlas): Cytosol; Plasma membrane
Pathways (Reactome):
Developmental Biology: Differentiation of Keratinocytes in Interfollicular Epidermis in Mammalian Skin
Immune System: Neutrophil degranulation
Gene Ontology:
Molecular function: protein binding; calcium ion binding; enzyme regulator activity
Biological process: epidermis development; microtubule cytoskeleton organization; signal transduction
Cellular component: extracellular region; ficolin-1-rich granule lumen
Genetic constraint (gnomAD): Loss-of-function variants: 0 observed, 0.16 expected, observed/expected ratio (o/e) 0, 90% interval 0 to 1.88. That is too few expected variants to judge how well the gene tolerates losing a copy. Missense variants: 207 observed, 202.5 expected, observed/expected ratio (o/e) 1.02, 90% interval 0.91 to 1.15. Synonymous variants: 101 observed, 91.88 expected, observed/expected ratio (o/e) 1.1, 90% interval 0.94 to 1.3.
Homologues: Orthologues: chimpanzee CALML5 (96% identical), macaque CALML5 (86% identical), pig CALML5 (60% identical), dog CALML5 (58% identical), rabbit CALML5 (55% identical), rat Calml5 (51% identical), mouse Calm4 (50% identical), Caenorhabditis elegans cal-1 (44% identical), mouse Calm5 (43% identical), Caenorhabditis elegans cal-3 (38% identical), Caenorhabditis elegans tnc-2 (37% identical), zebrafish cabp2a (34% identical), and 11 more. Paralogues in human: CALM1 (51% identical), CALM2 (51% identical), CALM3 (51% identical), CALML3 (47% identical), CETN1 (41% identical), CETN2 (38% identical), CABP4 (36% identical), CABP2 (34% identical), CALML6 (34% identical), CETN3 (34% identical), CABP1 (33% identical), CABP5 (33% identical), and 8 more.
Diseases named in the same sentence as CALML5 in open-access papers:
CALML5 is named in the same sentence as 30 diseases in open-access papers, as found by Europe PMC text mining. Sharing a sentence is not in itself a finding about the gene and the disease. The quoted sentences say what the papers report.
breast carcinoma (12 papers, 2017 to 2023). "Ubiquitination of CALML5 in the nucleus contribute to carcinogenesis of breast cancer, and K63-linked ubiquitination of CALML5 was found in breast cancer tissue, but not in healthy tissue." (PMID 36202787, 2022). "K63-linked ubiquitination of the CALML5-protein in premenopausal breast cancer patients is reported to be strongly implicated in carcinogenesis." (PMID 28157713, 2017). "Furthermore, using mRNA-seq and bioinformatics analyses, CALML5 was identified as a potential risk factor in the treatment of HER2+HR+ breast cancer." (PMID 36602226, 2023). "Our study provided potential molecular mechanisms why the combination of pyrotinib, letrozole, and dalpiciclib could achieve satisfactory clinical response and found CALML5 as a potential risk factor in the treatment of HER2+HR+ breast cancer." (PMID 36602226, 2023). "CALML5 could serve as a potential risk factor in the treatment of HER2+HR+ breast cancer." (PMID 36602226, 2023). "Our study provided evidence that the usage of dalpiciclib in the treatment of HER2+/HR+ breast cancer could partially abrogate the estrogen signaling pathway activation caused by anti-HER2 therapy and revealed that CALML5 could serve as a risk factor in the treatment of HER2+/HR+ breast cancer." (PMID 36602226, 2023). "However, the underlying mechanism of CALML5 in breast cancer warrants further investigation." (PMID 36602226, 2023). "Furthermore, CALML5 was revealed to be a risk factor in the treatment of HER2+/HR+ breast cancer and the usage of dalpiciclib might overcome the drug resistance to pyrotinib + tamoxifen due to CALML5 expression." (PMID 36602226, 2023). "CALML5 ubiquitination in the nucleus is involved in the carcinogenesis of breast cancer in young women." (PMID 32415241, 2020). "For example, B2M, CALML5, and HSPD1 are largely breast cancer–specific markers, but even these differ in their expression across the different three breast cancer PDXs." (PMID 36470535, 2023). "CALM2 and CALML5 were found to be significantly active in primary breast cancer, whereas CALML3 and CALML6 were significantly active in liver metastasis of breast cancer." (PMID 37958607, 2023). "We found that CALM2 and CALML5 were significantly active in primary breast cancer, while CALML3 and CALML6 were significantly active in breast cancer liver metastasis." (PMID 31557971, 2019). "Furthermore, the expression of CALML5 could be a potential risk factor in the treatment of HER2+HR+ breast cancer and the introduction of dalpiciclib could partially abrogate the drug resistance to pyrotinib + tamoxifen caused by the high expression of CALML5 in HER2+HR+ breast cancer." (PMID 36602226, 2023). "Ubiquitination of CALML5 may be involved in breast cancer, but its role in other cancers was not investigated yet." (PMID 35409691, 2022).
atopic dermatitis (3 papers, 2015 to 2022). "Higher CALML5 levels were implicated in terminal differentiation and barrier repair (atopic dermatitis)." (PMID 35755808, 2022).
oropharyngeal cancer (3 papers, 2021 to 2023). Carcinoma, predominantly squamous cell, arising from the epithelial cells of the oropharynx. "Moreover, the ‘HPV‐related CA cluster’ specifically expressed CALML5, which is closely associated with recurrence and survival outcomes in patients with HPV‐related cancers such as head‐and‐neck carcinoma and oropharyngeal cancer." (PMID 36967539, 2023). "Furthermore, methylation of the CALML5 gene, which may repress transcription, was associated with poor survival for HPV-positive oropharyngeal cancer patients." (PMID 34069237, 2021).
cutaneous melanoma (2 papers, 2023 to 2025). A primary melanoma arising from atypical melanocytes in the skin. "In cutaneous melanoma, calmodulin-like 5 (CALML5) has been identified as a core lactylation-associated gene, and the expression of which is significantly lower than that in normal skin tissues." (PMID 40046050, 2025).
glioma (2 papers, 2020 to 2021). A benign or malignant brain and spinal cord tumor that arises from glial cells (astrocytes, oligodendrocytes, ependymal cells). "The expressions of CALML5, CALM3 and CALML3 were upregulated in IDH mutant glioma." (PMID 34070840, 2021).
Anxiety (1 paper, 2019). Intense feelings of nervousness, tension, or panic often arise in response to interpersonal stresses. "Common variants in MTR, PPARA, ABCC3, CALML5, CACNB2 and PCDHB10 genes were associated with deficits in neurocognitive tests performance, whereas a variant in SLCO1B1 and EPHA5 genes was associated with anxiety and depression." (PMID 31181069, 2019). "Functionally predicted germline common variants in MTR, PPARA, SLCO1B1, ABCC3, CALML5, CACNB2 and PCDHB10 genes were found to be significantly associated with deficits in neurocognitive tests performance, whereas a variant in EPHA5 gene was significantly associated with both anxiety and depression." (PMID 31181069, 2019).
autoimmune disease (1 paper, 2021). A disorder resulting from loss of function or tissue destruction of an organ or multiple organs, arising from humoral or cellular immune responses of the individual to their own tissue constituents. "Eleven proteins (increased: ATP5B, CALML5, COLEC11, FCGBP, PLEK, PLXND1; decreased: APOB, ATP8B1, FAM20C, LOXL3, TIMD4) were significantly altered in bvFTD with autoimmune disease compared to those without autoimmune disease." (PMID 34539672, 2021).
cervical squamous cell carcinoma (1 paper, 2024). A squamous cell carcinoma arising from the cervical epithelium. "CALML5 was involved in the regulation of epidermal differentiation, and CALML5 silencing deteriorated cervical squamous cell carcinoma." (PMID 38672263, 2024).
head and neck cancer (1 paper, 2023). A primary or metastatic malignant neoplasm affecting the head and neck. "Only CALML5 showed significant prognostic value, while the prognostic value of CD59 and LIMA1 could not be validated in this cohort, emphasizing the necessity to assess the head and neck cancer specificity by subgroup analysis." (PMID 37274282, 2023).
head and neck squamous cell carcinoma (1 paper, 2023). A squamous cell carcinoma that arises from any of the following anatomic sites: lip and oral cavity, nasal cavity, paranasal sinuses, pharynx, larynx, and salivary glands. "A previous study showed that the high expression of CALML5 was strongly associated with better survival in patients with head and neck squamous cell carcinomas." (PMID 36602226, 2023).
lymph node metastases (1 paper, 2021). "In multivariate analyses, lymph node metastases, tumor differentiation, and CALML5 were independent prognosticators." (PMID 34069237, 2021).
Pick disease (1 paper, 2022). A rare neurodegenerative disorder leading to dementia. "Calmodulin-like skin protein (CLSP; aka calmodulin-like 5), which has four EF-hand domains and is functionally similar to CaM, is a potential biomarker for Pick’s disease." (PMID 36421678, 2022).
cancer (11 papers, 2017 to 2025). A tumor composed of atypical neoplastic, often pleomorphic cells that invade other tissues. "CALML5 methylation was observed in 31/42 (73.8%) of all samples, in 8/8 (100%) pre-treatment samples, in 8/9 (88.9%) cancer-bearing samples, and in 2/8 (25.0%) of the final samples in the series." (PMID 32415241, 2020). "Our approach to identify candidate cancer drivers revealed 4 possible novel candidate driver genes in OSCC: Firstly, CALML5 which encodes a skin-specific calcium-binding protein that is involved in epidermal differentiation." (PMID 28157713, 2017). "The known calcium-binding proteins (CALML5, S100A8, S100A14) modulate cancer therapeutics and survival." (PMID 38653992, 2024). "The markers CALML5, CD59, and LIMA1 were chosen based on their promising prognostic value presented in the Pathology Atlas and their perceived cancer cell specificity, as well as the availability of validated antibodies." (PMID 34069237, 2021). "Additionally, six hub genes (CALML5, CXCL10, KRT6C, KRTDAP, S100A7, SBSN) were uniquely elevated during the transition from HSIL to cancer, serving as potential biomarkers for early detection and intervention." (PMID 40612935, 2025).
tumor (11 papers, 2021 to 2025). "CALML5 is a calcium binding protein expressed in the upper layers of stratified epithelia and is known for its tumor suppressive properties." (PMID 39695857, 2024). "After knock down CALML5, the tumor seemed to be more sensitive to the treatment of pyrotinib + tamoxifen, and it showed similar response compared to the group treated with three-drug combination." (PMID 36602226, 2023). "N status, tumor differentiation, and CALML5 were significant, independent prognostic factors for 5-year DSS." (PMID 34069237, 2021). "For the OTSCC cohort, Cox regression analyses with forced entry were performed for variables significantly associated with 5-year DSS in univariate analyses (N status, tumor differentiation, lymphocyte infiltration, CALML5 protein expression, and LIMA1 protein expression)." (PMID 34069237, 2021). "Additionally, we observed that clusters 6, 7, 9 and 13 (CASP14, PRSS27, CALML5), which were enriched in CC, manifested high expression levels of genes related to carcinogenic pathways such as epithelial‐to‐mesenchymal transition, tumour cell proliferation, migration, invasion and angiogenesis." (PMID 36967539, 2023). "Moreover, KRT15, CALML5, and S100A2 have been described as having stem cell functions and EMP regulation, suggesting both tumor-promoting and tumor-suppressive roles." (PMID 39225101, 2024).
CALML5 also shares sentences with these, for which no sentence is quoted: melanoma (5 papers); Alzheimer disease (3); memory impairment (2); basal cell carcinoma (1); bladder cancer (1); cervical cancer (1); cervix (1); dementia (1); depression (1); Hydrocephalus (1); lung adenocarcinoma (1); metastasis (1); metastatic tumors (1); neuroblastoma (1); neurological disease (1); squamous cell carcinoma (1).